ATP13A3 (ATPase 13A3)
Description:
ATP-driven pump involved in endocytosis-dependent polyamine transport. Uses ATP as an energy source to transfer polyamine precursor putrescine from the endosomal compartment to the cytosol.
Synonyms: AFURS1; PPH5
Tractability: Antibody: UniProt predicts a signal peptide or a membrane-spanning region; the Human Protein Atlas places it where antibodies can reach. PROTAC: ubiquitination databases record sites on it; its protein half-life has been measured.
Gene: Protein-coding gene on chromosome 3 (194,402,672 to 194,498,364, reverse strand). Ensembl gene ENSG00000133657.
Subcellular location: Recycling endosome membrane; Early endosome membrane; Late endosome membrane
Subcellular location (Human Protein Atlas): Nucleoli; Cytosol; Plasma membrane
Gene Ontology:
Molecular function: ABC-type putrescine transporter activity; P-type transmembrane transporter activity; ATPase-coupled monoatomic cation transmembrane transporter activity; polyamine transmembrane transporter activity; ATP binding; ATP hydrolysis activity; nucleotide binding; P-type ion transporter activity
Biological process: intracellular calcium ion homeostasis; polyamine transmembrane transport; monoatomic cation transmembrane transport; putrescine transport; transmembrane transport
Cellular component: early endosome membrane; late endosome membrane; membrane; recycling endosome membrane
Genetic constraint (gnomAD): Loss-of-function variants: 44 observed, 132.21 expected, observed/expected ratio (o/e) 0.33, 90% interval 0.26 to 0.43. The upper end of that interval is the gene's LOEUF score, 0.43, which puts it in group 1 of 6, group 1 being the genes least tolerant of losing a copy. Missense variants: 1,041 observed, 1,429.8 expected, observed/expected ratio (o/e) 0.73, 90% interval 0.69 to 0.77. Synonymous variants: 450 observed, 476 expected, observed/expected ratio (o/e) 0.95, 90% interval 0.87 to 1.02.
Gene-disease validity (ClinGen):
ClinGen rates the evidence that ATP13A3 causes each of these diseases.
pulmonary arterial hypertension (semidominant): Definitive. Pulmonary arterial hypertension (PAH) is a group of diseases characterized by mean pulmonary artery pressure >20 mmHg and elevated pulmonary arterial resistance leading to right heart failure.
Homologues: Orthologues: macaque ATP13A3 (98% identical), chimpanzee ATP13A3 (97% identical), dog ATP13A3 (93% identical), pig ATP13A3 (92% identical), rabbit ATP13A3 (91% identical), rat Atp13a3 (90% identical), mouse Atp13a3 (89% identical), guinea pig ATP13A3 (88% identical), tropical clawed frog atp13a3 (76% identical), zebrafish atp13a3 (25% identical), Drosophila melanogaster SPoCk (14% identical), Caenorhabditis elegans catp-3 (14% identical), and 5 more. Paralogues in human: ATP13A4 (43% identical), ATP13A5 (40% identical), ATP13A2 (39% identical), ATP13A1 (23% identical), ATP2B2 (18% identical), ATP2B3 (17% identical), ATP2B1 (17% identical), ATP2B4 (17% identical), ATP2A2 (17% identical), ATP1A1 (17% identical), ATP1A2 (16% identical), ATP2A3 (16% identical), and 9 more.
Diseases named in the same sentence as ATP13A3 in open-access papers:
ATP13A3 is named in the same sentence as 30 diseases in open-access papers, as found by Europe PMC text mining. Sharing a sentence is not in itself a finding about the gene and the disease. The quoted sentences say what the papers report.
pulmonary arterial hypertension (11 papers, 2019 to 2025). "HMEC-1 cells are frequently used in the context of pulmonary arterial hypertension, a disease that is associated with ATP13A3 mutations, and do express ATP13A3." (PMID 36830711, 2023). "Taken together, our findings identify ATP13A3, which has been previously genetically linked with pulmonary arterial hypertension, as a major component of the mammalian polyamine transport system that confers sensitivity to MGBG." (PMID 33310703, 2021). "Although, reports implicate ATP13A3 gene mutations in the pathogenicity of pulmonary arterial hypertension (PAH) and its altered expression has been reported in cervical and pancreatic cancers, its regulation and molecular characteristics are still poorly elucidated." (PMID 35260637, 2022). "Potential loss-of-function variants of ATP13A3, the gene encoding a P5B-type transport ATPase of undefined function, were recently identified in patients with pulmonary arterial hypertension (PAH)." (PMID 38626311, 2024). "Moreover, heterozygous ATP13A3 mutations have been identified in pulmonary arterial hypertension." (PMID 33310703, 2021). "In detail, according to data available in the Human Protein Atlas and GTEx databases we prioritized ATP13A3 based on its expression in lung, cardiomyocytes and smooth muscle cells, which are involved in pulmonary hypertension vascular remodeling." (PMID 30679663, 2019). "In fact, forced miR-130a expression decreases ATP13A3, while the depletion of ATP13A3 induces an increase in miR-130/301 expression, suggesting a positive feedback loop that promotes endothelial cell apoptosis and pulmonary arterial hypertension." (PMID 38918813, 2024). "Rare missense ATP13A3 disease–associated variants have been identified in patients with pulmonary arterial hypertension (PAH), although their pathogenicity has not been confirmed." (PMID 38626311, 2024).
pancreatic cancer (10 papers, 2021 to 2025). "Indeed, ATP13A2 has been implicated in several human cancers, including melanoma, colon cancer, hepatocellular carcinoma, acute myeloid leukemia and non-small-cell lung cancer, while ATP13A3 has been linked to pancreatic cancer and colorectal cancer." (PMID 37371498, 2023). "In pancreatic cancer cells however, the expression level of ATP13A3 is inversely correlated with their sensitivity to polyamine transport inhibitors." (PMID 39981745, 2025). "ATP13A3 knockdown significantly decreased the growth of human pancreatic cancer cells under DFMO treatment." (PMID 39981745, 2025). "ATP13A3 was highlighted as the major importer of spermidine and spermine in human pancreatic cells, and metastatic pancreatic cancer cells displayed higher polyamine import and expression of ATP13A3 as compared to cells with slow proliferation." (PMID 39981745, 2025). "ATP13A3 is a P-type ATPase that is highly expressed in pancreatic cancer patients with unacceptable survival." (PMID 38722543, 2024). "For example, in human pancreatic cancer cells the polyamine transport protein ATP13A3 changes its localization pattern under conditions of polyamine depletion from the nucleolus to the plasma membrane to facilitate polyamine uptake." (PMID 37332717, 2023). "Here, we define the important role of ATP13A3 in polyamine transport in human cells using a panel of pancreatic cancer cells that differ in their ability to import polyamines." (PMID 35260637, 2022). "We assessed the expression, cellular localization and the response of the human ATP13A3 protein to polyamine treatments in different pancreatic cancer cell lines using Western blot and immunofluorescence microscopy." (PMID 35260637, 2022). "Further analysis of existing databases revealed that pancreatic cancer patients with high expression of ATP13A3 have decreased overall survival consistent with the role of intracellular polyamines in supporting tumor growth." (PMID 35260637, 2022). "Different pancreatic cancer cell lines demonstrate preferential expression of the ATP13A3 protein and exhibit distinct cytosolic and plasma membrane localization patterns in the presence of polyamine stimuli and polyamine-targeted therapies." (PMID 35260637, 2022). "The data indicate the presence of specific polyamine transport regulation in the different compartments of PDAC and support the reliance of pancreatic cancer cells on ATP13A3-mediated polyamine import, as we previously reported." (PMID 34945011, 2021). "Furthermore, recent studies have shown that ATP13A3 mutations account for the polyamine uptake deficiency in CHO-MG cells, and ATP13A3 facilitates polyamine transport in human pancreatic cancer cells, strongly implicating ATP13A3 as a polyamine transporter." (PMID 38626311, 2024). "Interestingly, high expression of ATP13A3 was found in metastatic pancreatic cancer cells with high polyamine uptake compared to slowly proliferating cells with low import activity." (PMID 37371498, 2023). "Here, we describe how ATP13A3, a P-type ATPase, functions as a polyamine transporter in response to different polyamine stimuli and polyamine-targeted therapies in highly proliferating pancreatic cancer cells." (PMID 35260637, 2022). "ATP13A3 expression has been highlighted as a potential biomarker for DFMO-based therapies in pancreatic cancers, suggesting that ATP13A3 may be a possible cancer target." (PMID 33310703, 2021). "Our previous study showed that siRNA knockdown of ATP13A3, a member of the P5-subfamily of the P-type ATPases, significantly decreased growth of DFMO treated human pancreatic cancer cells." (PMID 35260637, 2022). "This contrasts with a recent study that highlighted both SPD and SPM, but not PUT, as likely ATP13A3 substrates based on radiolabeled uptake experiments in pancreatic cancer cells." (PMID 36830711, 2023).
neuroblastoma (3 papers, 2023 to 2025). Neuroblastoma (NB) is the most common solid, extracranial childhood tumor. "An association between high ATP13A3 expression and poor survival in neuroblastoma further supports a role of this transporter in neuroblastoma progression." (PMID 39981745, 2025). "In this study we explored two candidate polyamine transporters, SLC3A2 and ATP13A3, as their higher expression is associated with an inferior outcome in neuroblastoma patients." (PMID 39981745, 2025). "Elevated ATP13A3 expression in neuroblastoma patients is associated with worse survival, which suggests that ATP13A3‐mediated polyamine uptake may contribute to malignant neuroblastoma phenotypes, similar to ODC1‐mediated polyamine biosynthesis." (PMID 39981745, 2025). "Based on our findings, ATP13A3 emerges as a major polyamine transporter in neuroblastoma that represents a target of the drug AMXT 1501." (PMID 39981745, 2025). "We therefore assessed the impact of ATP13A3 silencing on the growth and colony‐forming capacity of neuroblastoma cells." (PMID 39981745, 2025). "We demonstrated earlier that AMXT 1501 as a single agent inhibits neuroblastoma cell viability and colony formation similar to ATP13A3 silencing." (PMID 39981745, 2025). "Our database analyses revealed that ATP13A2 is expressed to similar levels as ATP13A3 in neuroblastoma patients and, contrary to ATP13A3 and SLC3A2 expression, high expression of ATP13A2 is predictive of a better outcome in patients." (PMID 39981745, 2025). "Combined, our experiments provide strong evidence for a key role of ATP13A3 in basal polyamine uptake in neuroblastoma cells." (PMID 39981745, 2025). "Collectively our findings underpin ATP13A3 as not only a primary driver of DFMO‐induced compensatory polyamine uptake in neuroblastoma but also a candidate target of AMXT 1501." (PMID 39981745, 2025). "Nevertheless, in a direct side‐by‐side comparison, ATP13A3 has a stronger impact on polyamine uptake than SLC3A2 in neuroblastoma cells under basal and DFMO‐treatment conditions." (PMID 39981745, 2025). "Supporting this finding, ATP13A3 mRNA levels were significantly higher in MYCN‐amplified versus non‐MYCN‐amplified neuroblastomas." (PMID 39981745, 2025). "To cross‐validate the polyamine transport function of ATP13A3 in neuroblastoma cells, we assessed the effect of ATP13A3 overexpression on mediating the cytotoxic effects of high intracellular polyamine levels." (PMID 39981745, 2025). "Our data thus provide compelling evidence that AMXT 1501 effectively targets ATP13A3‐mediated polyamine uptake in neuroblastoma cells, underscoring the therapeutic promise of ATP13A3 targeting in neuroblastoma." (PMID 39981745, 2025). "We demonstrated increased intracellular polyamine levels as well as an enhanced uptake of exogenous polyamines when ATP13A3 was overexpressed in neuroblastoma cells." (PMID 39981745, 2025). "Our work on neuroblastoma cells show that targeting ATP13A3, a polyamine transporter, with the inhibitor AMXT 1501 or gene silencing, combined with difluoromethylornithine treatment, effectively inhibits neuroblastoma cell growth." (PMID 39981745, 2025). "SLC3A2, ATP13A2, ATP13A3 are abundantly expressed in neuroblastoma tumors, while ATP13A4 and ATP13A5 expression is low." (PMID 39981745, 2025). "The growth and colony formation capacity of neuroblastoma cells were also reduced upon ATP13A3 knockdown, which is consistent with high ATP13A3 expression being predictive of poor outcome in neuroblastoma patients." (PMID 39981745, 2025). "Multivariate survival analyses on two neuroblastoma cohorts (Kocak GSE45547; SEQC GSE62564) that incorporated MYCN amplification, patient age and tumor stage as other prognostic variables, indicated that high ATP13A3 expression is an independent prognostic marker for neuroblastoma outcome." (PMID 39981745, 2025).
neuroblastoma (continued). "Similarly, high ATP13A3 expression was correlated with poorer outcome in two neuroblastoma cohorts, while for ATP13A2 the opposite was observed." (PMID 39981745, 2025). "Interestingly, we observed that, as previously found for SLC3A2, ATP13A3 expression was significantly higher in MYCN‐amplified versus non‐MYCN amplified neuroblastoma tumors." (PMID 39981745, 2025). "In this study, we discovered that high ATP13A3 expression is associated with worse overall and event‐free survival in neuroblastoma patients and that ATP13A3, but not SLC3A2, is a primary mediator of DFMO‐induced polyamine uptake in this disease." (PMID 39981745, 2025). "The discovery of ATP13A3 as the key driver in the hyperactive polyamine transport system of neuroblastoma may pave the way for developing more targeted strategies to attack cancer cells that heavily rely on increased polyamine import." (PMID 39981745, 2025). "Additionally, ATP13A3 knockdown increased the sensitivity of neuroblastoma cells to DFMO pointing to synergistic effects of blocking polyamine uptake via ATP13A3 and inhibiting polyamine synthesis with DFMO." (PMID 39981745, 2025). "To provide more conclusive evidence for AMXT 1501 inhibiting ATP13A3‐mediated polyamine uptake in neuroblastoma, we next assessed whether the activity of ATP13A3 can be effectively hindered by AMXT 1501." (PMID 39981745, 2025). "Thus, our study positions ATP13A3 as a primary polyamine transporter responsible for polyamine uptake in neuroblastoma." (PMID 39981745, 2025). "Despite being essential for cell physiology and survival, at high intracellular concentrations, polyamines are cytotoxic, and we utilized this phenomenon to provide further evidence for ATP13A3 functioning as a transporter mediating polyamine uptake into neuroblastoma cells." (PMID 39981745, 2025). "Thus, ATP13A3 WT overexpression confers higher polyamine‐induced toxicity to neuroblastoma cells as a consequence of excessive polyamine uptake." (PMID 39981745, 2025). "Hence, our data illustrate that neuroblastoma cells depend on ATP13A3‐mediated polyamine uptake to sustain their growth." (PMID 39981745, 2025). "Here, we show a role for ATP13A3 in the DFMO‐induced polyamine uptake in neuroblastoma cells suggesting that ATP13A3 may contribute to the resistance mechanisms employed by neuroblastoma cells following DFMO treatment." (PMID 39981745, 2025). "Since MYCN may have a stronger impact on the transcriptional regulation of ODC1 than of ATP13A3, neuroblastoma cells may be more dependent on biosynthesis and less dependent on polyamine uptake when MYCN is expressed." (PMID 39981745, 2025). "Conversely, overexpression of ATP13A3 in neuroblastoma cells increased polyamine uptake, which was inhibited by AMXT 1501, highlighting ATP13A3 as a key target of the drug." (PMID 39981745, 2025). "Our findings support a role for ATP13A3‐mediated polyamine uptake in both MYCN‐amplified and non‐MYCN amplified neuroblastoma cells." (PMID 39981745, 2025). "ATP13A3 silencing also sensitized MYCN‐amplified (KELLY) and non‐MYCN‐amplified (SH‐SY5Y) neuroblastoma cells to escalating DFMO concentrations, which resulted in reduced growth and colony‐forming capabilities." (PMID 39981745, 2025). "Our analysis suggests that ATP13A3 is a MYC target gene like ODC1 and SLC3A2 and that high expression of ATP13A3 represents an independent prognostic predictor of poor outcome in neuroblastoma." (PMID 39981745, 2025). "Reminiscent of ATP13A3 silencing, a sublethal dose of AMXT 1501 also sensitized MYCN‐amplified and non‐MYCN‐amplified neuroblastoma cells to DFMO in colony formation assays." (PMID 39981745, 2025). "Thus, this study identified ATP13A3 as a critical regulator of basal and DFMO‐induced polyamine uptake and a novel therapeutic target for neuroblastoma." (PMID 39981745, 2025).